INS (insulin)
Diseases named in the same sentence as INS in open-access papers (continued):
Sharing a sentence is not in itself a finding about the gene and the disease.
diabetes (continued). "Therapeutic choices for treating diabetes embrace sulfonylureas and alternative hypoglycemic agent secretagogues, alpha-glucosidase inhibitors, biguanides, thiazolidinediones, and insulin." (PMID 29670899, 2018). "CMPF exposition in vitro of beta-cells and in vivo of obese or insulin resistant models of mice accelerated diabetes development." (PMID 29783628, 2018). "For diabetes patients receiving reperfusion therapy, insulin is the preferred anti-diabetic drug, as it not only lowers the level of blood glucose but also decreases myocardial I/R injury by reducing myocardial apoptosis." (PMID 29912977, 2018). "The player progresses in the game by successfully directing the main character to control his diabetes and solve puzzles through the mini games that have educational goals, such as how to do insulin injections or how to balance blood glucose levels." (PMID 29385750, 2018). "Eighty percent of RIP-B7.1 mice immunized against insulin developed diabetes within 8 weeks, when receiving only a vehicle solution." (PMID 29662071, 2018). "Scenario analyses versus two recently marketed basal insulin analogs indicated that degludec would likely be cost-effective versus glargine 300 units/mL and biosimilar glargine across diabetes types and treatment regimens." (PMID 29549574, 2018). "Insulin resistance is the failure of insulin secretion to lead to the deposition of circulating glucose, which may occur due to a variety of causes, with the accumulation of fatty acids in cells being an important cause linking increases in adiposity and the development of diabetes." (PMID 29367240, 2018). "Diabetes mellitus (DM) is a metabolic disorder characterized by elevated levels of glucose in the blood resulting from defects in the action or secretion of insulin." (PMID 29594128, 2018). "The patient-centered treatment plan in the management of diabetes should focus specifically on matching the insulin supply to the regular diet/exercise patterns of diabetes patients and follow-up with regular SMBG." (PMID 29508275, 2018). "This study aims to compare TAG species and their fatty acid composition in adipose tissues from insulin sensitive (IS), insulin resistant (IR) and type 2 diabetes mellitus (T2DM) obese individuals." (PMID 29940972, 2018). "We adjusted for participants' age, gender, race, education, income, insurance status, insulin use, duration of diagnosed diabetes, and the number of prescribed diabetes medications." (PMID 30112462, 2018). "In the total study population, insulin secretion was highest in those with a single father with diabetes, lower in those with a mother with diabetes and lower still in those with both parents affected." (PMID 29274011, 2018). "In Asia, patients with type 2 diabetes mellitus (T2DM) often have suboptimal glycemic control for many years prior to initiating basal insulin." (PMID 29524190, 2018). "Pathways modulating glucose homeostasis independently of insulin would open new avenues to combat insulin resistance and diabetes." (PMID 30520733, 2018). "Age between 18 and 65 years, poor metabolic control, diabetes duration over 12 months, and use of basal and fast analogue insulin." (PMID 29791661, 2018). "Insulin is more likely to be used among patients with more severe diabetes mellitus of longer duration and more complications such as chronic kidney disease." (PMID 30053837, 2018). "Peptide-YY (PYY) and Glucagon-Like Peptide-1 (GLP-1) play important roles in the regulation of food intake and insulin secretion, and are of translational interest in the field of obesity and diabetes." (PMID 29311617, 2018). "Understanding and quantifying the dynamics of the human glucose-insulin control network is critical for the technological treatment of diabetes." (PMID 32232090, 2018). "With the diabetes course being longer, the decrease in insulin secretion capacity of islet β cells indirectly reflects the degree and speed of islet damage." (PMID 30552311, 2018).
diabetes (continued). "Additionally, diabetes-induced upregulation of the insulin signaling pathway in association with the activation of inflammatory markers led us to propose that there could be a correlation between insulin signaling and inflammation in renal tissues of diabetic rats." (PMID 30602713, 2018). "Despite this, only a limited number of studies have reported on the independent continuous associations of fasting plasma glucose (FPG), 2 h post-load glucose (2hPG), HbA1c and fasting insulin with incident type 2 diabetes mellitus." (PMID 29018885, 2018). "There was a decrease in blood sugars while fasting in men with diabetes during both insulin and saline visits." (PMID 30515210, 2018). "Diabetes mellitus, a major global public health challenge, is characterized by chronic hyperglycemia resulting from disturbances in insulin secretion, insulin action, or both." (PMID 29967293, 2018). "Use of other medications for diabetes was fairly common: repaglinide [37.2% (19/51)], sulfonylureas [31.3% (16/51)], insulin [17.7% (9/51)], and thiazolidinedione [13.8% (7/51)]." (PMID 29211393, 2018). "In older men, these diseases were joined by Diabetes, non-insulin dependent in the first year, adding Cataract in the remaining 5 years." (PMID 29338690, 2018). "Our data reveal that most CHI patients with diabetes appear to be treated less intense than T1D patients, as significantly more CHI patients with diabetes are treated with conventional insulin therapy, both at diabetes onset and at follow-up." (PMID 30577875, 2018). "As SST5 is expressed on the pancreatic β-cells, SRIF analogs with higher SST5 affinity (pasireotide > octreotide and lanreotide) suppress insulin secretion, leading to hyperglycemia and diabetes." (PMID 30232095, 2018). "HK3, FCN1,CAMK1, GLUT1/SLC2A1 and GLUT3/SLC2A3 are involved in glucose and insulin metabolism that played vital role in development of obesity and diabetes." (PMID 29876008, 2018). "Insulin resistance, which is defined as a defect in the ability of insulin to drive glucose into its target tissues, predicts and precedes the development of type 2 diabetes mellitus." (PMID 29558390, 2018). "The diabetic phenotype associated with HNF1β mutations is also equally heterogenous, with severity of glycaemia ranging from impaired glucose tolerance to diabetes requiring insulin therapy." (PMID 29764441, 2018). "Among those who said they had diabetes, questions were asked regarding age at diagnosis and insulin and oral hypoglycemic medication use." (PMID 29596402, 2018). "Type 2 diabetes mellitus (T2DM) is a chronic disease characterized by hyperglycemia and dyslipidemia caused by impaired insulin secretion and resistance of the peripheral tissues." (PMID 29599810, 2018). "Before surgery 13 patients were diagnosed with diabetes, 10 of these used oral anti-diabetic drugs or insulin." (PMID 29401505, 2018). "Studies have shown that humanin protects against stroke in mice, ameliorates atherosclerotic plaque formation, improves insulin sensitivity in rodent models of diabetes, and affords cardioprotection against myocardial ischemia." (PMID 30042784, 2018). "Similar findings were reported in a cross-sectional analysis among individuals with diabetes, which highlights the potential role of vitamin D in glucose metabolism and insulin sensitivity." (PMID 29888290, 2018). "BCM accumulation is independent of food intake, except protein, and depends on normal physiologic adjustments of pregnancy, which are upset by insulin lack in diabetes." (PMID 30275385, 2018). "The diabetes is newly diagnosed in these patients at the time of their admission to the hospital for insulin treatment." (PMID 30280274, 2018). "Diabetes was diagnosed in 89 (23%) patients: when last observed, 14 patients (9 women, 5 men) were being treated with insulin, 34 (21 women, 13 men) with oral hypoglycemic agents, and 41 (33 women, 8 men) with dietary treatment." (PMID 29492700, 2018).
diabetes (continued). "The target LDLc was more often reached by patients with more serious disease, as indicated by a longer duration of type 2 diabetes mellitus, more frequent insulin use, and higher prevalence of microvascular complications." (PMID 29695715, 2018). "Consensus evidence-based guidelines for insulin initiation, optimization and continuation in type 2 diabetes mellitus." (PMID 29527102, 2018). "According to American Diabetes Association, Type 2 Diabetes mellitus (T2DM) is a “group of metabolic diseases characterized by hyperglycemia resulting from defects in insulin secretion, insulin action or both”." (PMID 30114196, 2018). "As reported in our previous study, the multivariable analysis showed a second-order interaction between diabetes duration, the presence of diabetic retinopathy, and insulin therapy (p = 0.003)." (PMID 29530048, 2018). "FPG was most strongly associated with incident diabetes, followed by 2hPG, HbA1c, HOMA-IR and fasting insulin." (PMID 29018885, 2018). "Our study suggests the potential of a low-fat plant-based diet in diabetes prevention, addressing both core pathophysiologic mechanisms—insulin resistance and diminished beta-cell function—at the same time." (PMID 29425120, 2018). "For the transition from IV to SC insulin administration in inpatients with diabetes, current guidelines suggest administering 60–80% of the total daily insulin infused dose as basal insulin." (PMID 30918874, 2018). "We found that patients taking a combination of insulin and oral medication were more likely to develop foot ulcer than were patients whose diabetes was managed with either oral glycemic agent or insulin alone." (PMID 30559788, 2018). "Diabetes mellitus is a group of metabolic diseases in which hyperglycemia results from either defective insulin secretion or insulin action or both." (PMID 29872590, 2018). "Almost half had a glycemic disturbance at diagnosis (26% diabetes and 21% prediabetes, respectively), while less than a tenth had any disturbance after surgery (all diabetes, the majority on insulin, but all had improved glycemic control)." (PMID 30220006, 2018). "All patients were diagnosed with diabetes at less than 6 months of age and transferred from insulin to sulfonylureas between 0·2 and 34·5 years." (PMID 29880308, 2018). "In fact, Japanese with normal glucose tolerance already showed an insulin secretion ability similar to Caucasian diabetes patients." (PMID 29549240, 2018). "In-hospital observation is typically recommended for patients who present to the emergency department with symptomatic hypoglycemia who are taking oral diabetes medications or long acting insulin." (PMID 29799604, 2018). "In the Hispanic-Latino population, patients with diabetes often show reluctance to start insulin therapy, frequently due to myths and misconceptions about its use." (PMID 30116737, 2018). "Attending DM classes was significantly associated with general knowledge about diabetes (p 0.026) while the level of education was an independent determinant of Total Knowledge and Insulin use knowledge scores." (PMID 30050608, 2018). "Insulin-stimulated glucose uptake through GLUT4 is attenuated in diabetes, which, especially in type 2 diabetes, is one of the major pathophysiological features of cardiomyocytes." (PMID 30138395, 2018). "Even though there have been advances in the understanding of the pathogenesis and control of both forms of diabetes, therapeutic methods including insulin injection remain unsatisfactory." (PMID 30065848, 2018). "Chronic HIV infection has been reported to contribute to insulin resistance and diabetes by up-regulating inflammatory chemokines involved in insulin regulation." (PMID 29769110, 2018). "Insulin omission was more frequent among women (50.8%), and age and duration of diabetes were lower in the low adherence group (50 and 6 years, resp)." (PMID 30116737, 2018).
diabetes (continued). "Participants with cardiovascular complications had more frequent diabetes mellitus, particularly those requiring insulin therapy (51.7% vs. 24.7%, p=0.012, that is, 34.5% vs. 9.7%, p=0.003)." (PMID 30271785, 2018). "Nevertheless, we applied an inclusion criterion for known diabetes duration ≤5 years to keep the study group homogenous and the pancreatic insulin production preserved." (PMID 30619502, 2018). "Treatment with empagliflozin in rats with tacrolimus-induced diabetes reduced hyperglycemia and increased plasma insulin levels and islet size; it also enhanced glucose-induced insulin secretion in isolated pancreatic tissue." (PMID 29411291, 2018). "Diabetes experts considered this mandated therapy change to the disadvantage of patients, as insulin degludec offers a unique safety profile and a longer half-life." (PMID 30229501, 2018). "d-ribose was first found to down-regulate blood glucose and up-regulate insulin levels, and thus “oral administration of d-ribose in diabetes mellitus” was described in 1957." (PMID 30101366, 2018). "Among the molecular mechanisms of action that relates to diabetes is the insulin secretion mechanism which occurs in the pancreatic beta cell." (PMID 30046337, 2018). "Within this population, remote adjustment of basal insulin for patients with diabetes is an appealing option." (PMID 29555621, 2018). "The system also needs to consider how to integrate specialist diabetes support to help the primary care teams in their clinical decision making and in building the resources that patients will need to support their insulin use." (PMID 29788908, 2018). "The most popular sessions included Diabetes Burnout (n=17), Your Rights (n=15), Diabetes Technologies (n=15), and Exercise and Nutrition (n=15); these were followed by Transition to Adult Clinic (n=14); Sex, Insulin, and Rock-n-Roll (n=14); and Say What?" (PMID 30401674, 2018). "Regarding the pathogenesis of diabetes fewer than half of the respondents were knowledgeable of the relationship of insulin to diabetes." (PMID 29986694, 2018). "In patients with type-2 Diabetes Mellitus, insulin-mediated glucose uptake in the skeletal muscle improved, probably due to increase in femoral artery blood flow." (PMID 30183742, 2018). "Other study had suggested that the presence of islet autoantibodies in older age-group diabetes was a weaker predictor of insulin requirement than that in younger group." (PMID 29887833, 2018). "Insulin resistance is recognized as dysfunction of this insulin signal transduction in glucose uptake into skeletal muscles in type 2 diabetes mellitus." (PMID 30347717, 2018). "Insulin signaling governs metabolic homeostasis and cell growth, and its dysregulation leads to metabolic disorders, such as diabetes." (PMID 30555826, 2018). "Accordingly, therapeutic strategies for the treatment of diabetes aim to improve insulin sensitivity (thiazolidinediones) or augment insulin secretion from the pancreatic β-cell (sulphonylurea receptor inhibitors)." (PMID 29371604, 2018). "We identified numerous DEGs, which are potentially associated with oxidoreductase activity, ATPase activity, amino catabolic processes, type 2 diabetes mellitus, and insulin signaling pathways." (PMID 30158951, 2018). "The time since the diabetes diagnosis ranged from four to 33 years, with a mean time of 15.4 years and two patients also reported to be insulin-requiring." (PMID 30005696, 2018). "Diabetes is a chronic disorder characterized by hyperglycemia due to decreased levels of insulin or the inefficiency of the tissue to use it effectively." (PMID 30360409, 2018). "Those patients who experienced severe hypoglycaemia had a longer duration of diabetes, greater insulin use and a higher incidence of heart failure and kidney disease at baseline." (PMID 28913543, 2018). "Diabetes Mellitus is a pandemic disorder mainly characterized by hyperglycemia due to defect in insulin secretion, insulin action or both." (PMID 29572460, 2018).
diabetes (continued). "Use of the insulin guidance service achieved improved glycemic control by optimizing insulin dosing, which enabled most patients using the service to reduce or eliminate the use of expensive diabetes medications." (PMID 32685571, 2018). "Type 2 diabetes mellitus (T2D) is an outcome of combined effect of insulin resistance and insufficient insulin secretion from the pancreatic β cells." (PMID 30072892, 2018). "The discovery of insulin has been a milestone in that has truly revolutionized both the therapy and the prognosis of the diabetes." (PMID 30405529, 2018). "Special attention should be given for patient with a longer duration of diabetes and those who are taking insulin therapy." (PMID 29505602, 2018). "The strongest association between NAFLD and CACS was observed in subjects with few metabolic risk factors according to diabetes status, hypertension, LDL, HDL, triglycerides, hsCRP and insulin." (PMID 30133541, 2018). "In the United States, the National Health and Nutrition Examination Survey (2005–2012) reported that the proportion of patients with diabetes on any insulin (includes insulin only and insulin plus oral diabetes medications) was 29.1% (95% CI 26.7–31.5)." (PMID 30116737, 2018). "Adiponectin gene (ADPN) serves as a protective factor in preventing diabetes progression by suppressing inflammatory responses and increasing insulin sensitivity." (PMID 29736170, 2018). "Their antioxidant characteristics and effects on insulin secretion, glucose absorption, and gluconeogenesis make them potent candidates towards treating diabetes." (PMID 29813110, 2018). "If the body stops making insulin, or cells stop responding to it, blood sugar levels rise, leading to diabetes." (PMID 30412050, 2018). "Evidence from experimental and clinical studies demonstrates the beneficial effects of n-3 PUFA consumption during diabetes on insulin function, oxidative stress, and in vivo lipid peroxidation." (PMID 29695082, 2018). "Consistently, insulin requirements are lower in CHI patients with diabetes compared to patients with T1DM, particularly as diabetes progresses." (PMID 30577875, 2018). "The overall good metabolic control of all patients in the present study likely reflects intensive diabetes treatment by either insulin or oral glucose-lowering medication." (PMID 30159333, 2018). "In contrast, all seven vaccinated SOCS1-tg mice were protected from diabetes and showed normal pancreas morphology on day 21 p.i. with healthy exocrine tissue and intense insulin and glucagon staining in the islets of Langerhans." (PMID 29151123, 2018). "Lee P, Chang A, Blaum C, Vlajnic A, Gao L, Halter J. Comparison of safety and efficacy of insulin glargine and neutral protamine hagedorn insulin in older adults with type 2 diabetes mellitus: results from a pooled analysis." (PMID 29527102, 2018). "Patients with diabetes in Taiwan are typically highly resistant to using insulin, and therefore are late in the course of their disease before they are willing to accept insulin therapy." (PMID 30143020, 2018). "Family history of diabetes should also be considered in future work since individuals with a diabetic parent exhibit a blunted post-exercise insulin-mediated glycogen storage response." (PMID 30061841, 2018). "Variable degrees of insulin resistance and impaired insulin secretion are major pathophysiological characteristics of type 2 diabetes mellitus (DM)." (PMID 30419056, 2018). "Since metformin can enhance insulin sensitivity and improve metabolic syndrome, it has been used not only for treating diabetes patients, but also for treating osteoporosis patients and individuals with metabolic syndromes barely affecting glucose levels." (PMID 30134793, 2018). "Participants who had experience with two non-insulin injection devices also completed the draft Diabetes Injection Device - Preference Questionnaire (DID-PQ)." (PMID 30294714, 2018).